CD4 (CD4 molecule)
Diseases named in the same sentence as CD4 in open-access papers (continued):
Sharing a sentence is not in itself a finding about the gene and the disease.
cancer (continued). "For example, the expression of JAK1, which is located on chromosome 1p31.3, also had significant positive correlations with infiltrating levels of CD8+ T cells, CD4+ T cells, macrophages, neutrophils, and dendritic cells in cancer." (PMID 34335194, 2021). "CCL20 was the ligand of CCR6 and reported to be accountable for recruiting CD4+ T cells to promote STAT3 activation to foster cancer stemness." (PMID 33514440, 2021). "In particular, cancer neoantigens are generated as the consequence of genetic damage accumulated during cancer progression and provide ideal immunological targets for host CD4+ and CD8+ T cells." (PMID 34771703, 2021). "Our study suggested that cancer patients in T3-4 stages had lower levels of CD3+CD4+ T cells and CD19+ B cells, and patients in N2-3 stages had lower levels of CD19+ B cells and higher levels of IL-2." (PMID 34712741, 2021). "In the T1D sphere, HIPs were reported as T cell epitopes before spliced peptides were; however, spliced peptides as epitopes for CD8+ T cells in cancer immunology were discovered over a decade before HIPs were described as CD4+ T cell targets." (PMID 34044020, 2021). "We also note that cancer is one of the most significant disease categories that emerged from the IPA analysis of the genes in CD4+ T cells TADs." (PMID 33894768, 2021). "DNMT1 is closely related to the occurrence and development of various diseases, including several types of cancers, as it affects the methylation levels of CD4+T cell-related genes, thereby inhibiting the immune response 81-84." (PMID 34512165, 2021). "Future research will be crucial to elaborate immune checkpoint regulation of CD4+ TH cell differentiation and function and identify new nodes in the network for therapeutic targeting in cancer." (PMID 34012451, 2021). "Dendritic cells (DCs) are known for their role in presenting cancer cell antigens to CD4+ T cells via the JAK/STAT signaling pathway." (PMID 34685635, 2021). "Meanwhile, CD4+ T cell activation has evolved as an essential goal of cancer vaccines, whereby two main strategies are used." (PMID 33546283, 2021). "Since CD4+ T cell exhaustion is far less studied, especially in the context of cancer, prospective research is required to reveal the role of these transcription factors in their full extent." (PMID 34548096, 2021). "The survival analyses based on the cancer genome atlas (TCGA) database showed that CD4 memory resting T cells would be a predictive outcome signature in NPC." (PMID 34395318, 2021). "These prompt a number of key outstanding questions regarding the biology of cytotoxic CD4+ T cells in human cancer that must be carefully weighed in future correlative or ex vivo functional studies of these cells." (PMID 34910940, 2021). "The CD8+ T-cell and CD4+ T-cell are the principal weapons of immunity against cancer, but prolonged immune responses can result in extended tissue damage, resulting in fatal immunopathology." (PMID 34371830, 2021). "This is consistent with previous research, which revealed that more resting memory CD4+ T cells existed in ER+ cancers." (PMID 34220957, 2021). "Endothelial cells appeared as receiver cells for 5 of the top 30 CC pair biomarkers (with CD4+ T cells, B cells, cancer cells, adipocytes, and endothelial cells as sender cells)." (PMID 34430923, 2021). "These promising clinical findings are associated with the activation of natural killer cells, cytotoxic CD8+ T cells and CD4+ T cells, which are the most relevant immune responses to cancer." (PMID 34737957, 2021). "Peter Cohen, MD was an early advocate for CD4+ T cell therapy for cancer, at a time when most of the field was focused almost exclusively on CD8+ CTL." (PMID 34012451, 2021). "Beginning as a Physician Scientist at UC San Diego, he spent many years at NCI, in both Surgery and Medicine Branches, working on advancing the concept that CD4+ T cells were critical to immunotherapy for cancer." (PMID 34012451, 2021).
cancer (continued). "Other immune components such as CD4+ T cells are also required to eradicate cancer recurrence by different mechanisms." (PMID 33446671, 2021). "Conversely, anti-cancer immune cells, M1 macrophages, and activated memory CD4 T cells both had lower infiltration in octogenarians in the METABRIC cohort (both p < 0.05)." (PMID 34208219, 2021). "Clinical outcomes depend on the level of TILs in the TME, as an augmentation of CD4+, CD8+, and NK cells in the early stage of a malignant tumor is associated with a favorable prognosis." (PMID 33738337, 2021). "It has been reported that some CD4+ T cells are essential for tumorigenesis and involved in different human cancers 25-27." (PMID 33390778, 2021). "As proposed by Dunn and Schreiber, three essential phases characterize the interactions between cancer and IS cells: Elimination by NK, CD4+, and CD8+ T cells, equilibrium, and escape from cancer immune surveillance." (PMID 33806300, 2021). "The percentage of CD8+ T cells increased and was significantly greater than CD4+ T cells after co-culturing with EpCAM-positive cancer SW480 cells for 48 h." (PMID 34790117, 2021). "TIMER was used to evaluate the association between SOCS3 and infiltrating immune cells, including CD4+ T cells, CD8+ T cells, B cells, cancer associated fibroblasts (CAFs), NK cells, macrophages and endothelial cells." (PMID 34120621, 2021). "We found that HSF1 significantly correlated with the infiltration levels of B cells, CD8+ T cells, CD4+ T cells, macrophages, neutrophils, and DCs in many cancers." (PMID 34239690, 2021). "In restimulated CD4+ T cells, the p21 expression increases, although the co-culture of CD4+ T cells with MDA-MB-231 cancer cells induces a dramatic elevation of p21." (PMID 34439305, 2021). "We found that five immune cells (CD4+ T cells, CD8+ T cells, neutrophils, endothelial cells, and cancer associated fibroblast cells) were associated with OS of BCa." (PMID 35127724, 2021). "By ranking mutated peptides encoded by mutations detected in nine cancer patients, VENUS was able to select in the top 60 ranked peptides, the 95% of neoantigens experimentally validated including both CD8 and CD4 T cell specificities." (PMID 34452005, 2021). "In some advanced cancers, it has been demonstrated that there are accumulating and infiltrating CD4+CD25high T cells surrounding tumors." (PMID 34055618, 2021). "In TCGA, a high KDM1A mRNA level correlated significantly with a high TIL percentage, low fraction of CD8+T cells, high fraction of CD4+T cells and high level of cancer/testis antigens (CTAs) (p = 0.039, 0.038, 0.012, 0.009, respectively)." (PMID 33799951, 2021). "In cancer, the opportunity to convert immune-suppressive TA-Tregs into antitumor effector CD4+ T cells remains an attractive therapeutic aim." (PMID 33924428, 2021). "Reciprocally, inhibition of the PI3K/AKT/mTOR pathway has shown to control CD4+ regulatory T-cells activity and enhance cancer cell recognition by the immune system in vivo." (PMID 33546207, 2021). "For patients with a CD4 count of ≤ 199/mm3, 50% had early-stage cancer, while 50% had late-stage cancer." (PMID 34691768, 2021). "Other studies previously reported about the presence of cytotoxic CD4 T cells in different human diseases, still the direct cytotoxic potential of CD4 T cells has only been shown in some cancer patients." (PMID 34064410, 2021). "The most significant DHS enrichments were observed in cell lines derived from blood lymphocytes (e.g. CD4+), skin (e.g. iPS), cancer (e.g. HeLa), embryo (e.g. embryonic stem cells) and in tissues from fetal brain." (PMID 33420178, 2021). "Our data show that T cells specific for the cancer testis Ag NY-ESO-1 are solely found within the PD-1hiCD39+ CD4 TIL population." (PMID 33332284, 2021). "The meta-analysis of CD4+ helper T-cells also revealed higher infiltration in normal and cancer tissue and lower infiltration in lgCIN and hgCIN tissue, most notably in hgCIN." (PMID 33257839, 2021).
cancer (continued). "Cytotoxic CD4+ T cells are also detected in human cancer, as shown most recently by single-cell genomic surveys, posing important questions as to their biological and clinical relevance." (PMID 34910940, 2021). "CD4+ T cells with phenotype compatible with senescence have been also detected in patients with cancer." (PMID 34386013, 2021). "Heat killed Py230 cells were added to the cultures to obtain a final CD4+T cell to (heat killed) cancer cell ratio of 1:10." (PMID 33918403, 2021). "RDM1 expression was also correlated with the degree of immune infiltration of B cells, CD8+ T cells, CD4+ T cells, macrophages, neutrophils and DCs in 16, 9, 12, 17, 12 and 14 cancer types, respectively." (PMID 34435618, 2021). "As anticipated, all immune subpopulations were represented as lying in opposition to cancer cellularity, in particular M1 macrophages, CD4+ memory resting T cells, and CD8+ T cells." (PMID 34549724, 2021). "In this communication, we utilized a novel approach to expand the effector phenotype of CD4+T cells which retained their in vivo anti-cancer efficiency." (PMID 33918403, 2021). "Most patients had CD4 count greater than 200 (cells/mL) at time of cancer diagnosis (72.6%, n = 159)." (PMID 34225709, 2021). "RP11‐89 was significantly correlated with the expression of CD44, CD70 and LAGLS9 in pan‐cancers and was significantly associated with the abundance of activated CD4 T cells, activated CD8 T cells and effector memory CD4 T cells in pan‐cancers." (PMID 33797188, 2021). "Under the same conditions, B6H12 mediated phagocytosis of cancer cells reduced the ability of macrophages to stimulate CD4+ T cell proliferation but also, significantly reduced the percentage of CD4+FOXP3+ regulatory T cells in co-culture." (PMID 34603322, 2021). "Meanwhile, ex vivo studies of cytotoxic CD4+ T cells from human cancer patients points to variable overexpression of either TBX21 or RUNX3 plus BLIMP-1 (via PRDM1) when compared with non-cytotoxic CD4+ T cells." (PMID 34910940, 2021). "High PHF19 levels were critically associated with the infiltration of myeloid-derived suppressor cells (MDSCs) and Th2 subsets of CD4+ T cells in most cancers." (PMID 35069553, 2021). "During the exhaustion process that occurred in CD4+ T cells grown with cancer cells, the PD-L1 expression was strongly elevated compared to control CD4+ T cells." (PMID 34439305, 2021). "A recent pan-cancer analysis of over 10,000 samples from 23 cancer types revealed a significantly higher infiltration of B cells, CD4, and CD8 T cells in HPV-positive HNSCC than HPV-negative HNSCC." (PMID 34659220, 2021). "We found high overexpression of PD-L1 at both the transcriptomic and protein levels in CD4+ T cells co-cultured with MDA-MB-231 cancer cells." (PMID 34439305, 2021). "The PD-L1 overexpression was also observed in CD4+ T cells after co-cultivation with other cell lines overexpressing PD-L1, which suggested the existence of a general mechanism of CD4+ T cell exhaustion induced by cancer cells." (PMID 34439305, 2021). "The ratio between CD8+ and CD4+ cells to FoxP3+CD8+ Tregs is a key prognostic factor for different types of cancer." (PMID 34707136, 2021). "This emphasizes the need to incorporate PLWH with low CD4 cell counts into clinical trials and guidelines for cancer treatment." (PMID 34941669, 2021). "Normal CD4+ T cells were more resistant than cancer lymphocytes, and a significant decrease in cell viability was observed at concentrations higher than 10 U/mL." (PMID 34948436, 2021). "Killer-type lectins are also of interest as markers of cytotoxic CD4+ T cells, and in the GZMB+ subset, KLRG1 is consistently associated with these cells in both human cancers and human dengue viral infection, consistent with an effector phenotype." (PMID 34910940, 2021).
cancer (continued). "Although such reports are uncommon, they highlight the fact that CD4 T cells with a cytolytic potential infiltrate tumors, can be expanded for cellular therapy and mediate objective responses in cancer patients after adoptive transfer." (PMID 34201655, 2021). "When tested in combination with nutlin-3, the expression of MDM2 in cancer cells was increased which in turn increases the anti-tumour response of the CD4+ T cells." (PMID 35071005, 2021). "The CD8+/CD4+Foxp3+ ratio is known to be a marker that correlates with prolonged cancer patient survival." (PMID 34439192, 2021). "Tregs are CD3+ CD4+ CD25+ FOXP3+ CD127low T cells that are recruited by cancer cells via surface ligands like CCL22 and CCL35." (PMID 33530455, 2021). "In particular, we assessed B cells, CD4+ T cells, CD8+ T cells, macrophages and dendritic cells, as immune infiltrates, while cancer associated fibroblasts and endothelial cells were analysed as infiltrating non-immune cell types." (PMID 34094919, 2021). "The prior body of work characterizing the features, function, and ontogeny of cytotoxic CD4+ T cells outside of cancer provides important context but must be carefully interpreted for context dependence when extrapolating to cancer patients." (PMID 34910940, 2021). "YTHDF1 expression had a strong relationship with dendritic cell in 12 cancer types, macrophage in 9 cancer types, neutrophil in 8 cancer types, CD8+ T cells in 13 cancer types, B cells in 10 cancer types and CD4+ T cells in 6 cancer types." (PMID 34026603, 2021). "This study suggests that the benefits of ART in cancer prevention go beyond restoration of CD4 lymphocyte suppression and are long-standing, at least through childhood, if therapy is continued." (PMID 33803641, 2021). "Tapasin-related protein is a T cell co-inhibitory molecule identified in 2021, which is expressed on cancer cells and antigen-presenting cells as well as the corresponding receptor on activated CD4 and CD8 T cells." (PMID 35003017, 2021). "We assessed the correlation between the expression levels of the hub genes and the gene expression profiles suggestive of B cell, CD8+ T Cell, CD4+ T Cell, macrophage, neutrophil, and dendritic cell infiltrations across the hub cancers." (PMID 34359748, 2021). "M1 macrophages are known to inhibit cancer progression, CD4+T-cells can recognize cancer antigens, CD8+T-cells can inhibit cancer metastasis, and immune infiltration of T-cells can significantly influence the efficacy of immunotherapy." (PMID 35096010, 2021). "Our study aims to uncover how CD8+ T cells can be helped by CD4+ T cells or modified in order to improve their effector function against cancer." (PMID 33809259, 2021). "CD73 was mainly expressed on CD45+ immune cells in cancer tissues, and CD4+ T cells and CD8+ T cells were the cell types accounting for most of the total CD73 expression." (PMID 34753903, 2021). "T-cell subsets such as CD3+, CD4+, CD8+ and CD4+/CD8+ can directly reflect the postoperative immune functions of cancer patients." (PMID 34666774, 2021). "An increasing number of clinical studies incorporate this knowledge in order to develop more efficient drug products, and evidences are accumulating that CD4+ T cell subsets are the main players in various cancer immunotherapies." (PMID 33546283, 2021). "Our findings suggested a significant correlation between the SLC39A family gene expression and B-cell infiltration in broad cancer types and CD4+ T cells, CD8+ T cells, Treg T cells, macrophages, and neutrophils in specific tumors." (PMID 34925450, 2021). "The upregulation of the HSF1 expression corresponded to a poor prognosis in patients and correlated with the infiltration levels of B cells, CD8+ T cells, CD4+ T cells, macrophages, neutrophils, and DCs in diverse cancers." (PMID 34239690, 2021).
cancer (continued). "We previously found that administration of gene-modified T cells in clinical trials can elicit high-magnitude CD8+ and CD4+ responses to foreign transgene–encoded antigens, even in highly immunocompromised patients, which suggested that this could be a novel cell-based vaccine platform for cancer." (PMID 34396986, 2021). "Due to the complexity of the underlying molecular pathways, the modeling of biological systems has emerged as a promising solution for better understanding both CD4 + T cell differentiation and cancer cell behavior." (PMID 34026764, 2021). "The evolving themes we have highlighted illustrate a renewed appreciation of the central role of CD4+ T cells directed against cancer." (PMID 32457487, 2021). "Cancer cells can inhibit Th-1 polarization or decrease CD4+ T cell levels in the metastatic TME to favor cancer cells survival." (PMID 36046433, 2021). "Heat map data suggested that TIICs like cancer-associated fibroblasts, B cells, CD8+ T cells, macrophages, and CD4+ T cells were highly expressed in metastatic CM compared to primary CM by EPIC." (PMID 33829062, 2021). "while for BAF155, BAF170, and INI1 subunits of the SWI/SNF complex, the protein levels confirmed transcriptomic data, indicating aberrant function of SWI/SNF CRC during exhaustion in CD4+ T cells induced by MDA-MB-231 cancer cells." (PMID 34439305, 2021). "Cancer TIME is critical for the differentiation of naive CD4(+) T cells (Th0) into Th17 and Treg/Th17 balance." (PMID 33801021, 2021). "Mice exposed to recombinant VEGF at similar concentrations to those observed in patients with advanced cancer develop a thymic atrophy with a reduced number of CD4/CD8 thymocytes." (PMID 33854498, 2021). "Animal proof-of-concept studies using RNA replicons revealed that neoantigen-based cancer vaccines designed with Ancer are immunogenic, induce multifunctional CD4+ and CD8+ T cell responses, and are effective in challenge experiments." (PMID 33976291, 2021). "Similar to data from China21 and France, our cohort showed significantly reduced CD3 and CD4 lymphocytes in cancer subjects." (PMID 34786866, 2021). "For stroma, the marker genes used were VWF, ENG, and CDH5 (for endothelial cells), DCN, ACTA2, and FAP (for cancer-associated fibroblasts), and PTPRC, CD4, and CD163 (for leukocytes)." (PMID 33810510, 2021). "The TIMER analysis results show that UBE2C expression was significantly associated with the abundance of CD8+ T cells in 25 cancers, CD4+ T cells in 29 cancers, neutrophils in 29 cancers, DCs in 31 cancers, macrophages in 28 cancers, and B cells in 30 cancers." (PMID 34858987, 2021). "Surprisingly, the decreased expression of 676 genes was found in CD4+ T cells after co-culture with cancer cells (T15M) in comparison to 523 specifically downregulated genes in the control (T15)." (PMID 34439305, 2021). "As high salt induced differentiation to effector CD4+T cell phenotype, we next determined the anti-cancer efficiency of these activated CD4+T cells." (PMID 33918403, 2021). "In a murine model, we demonstrate that, even in the absence of defined adjuvant signals, Tvax induces robust CD8+ and CD4+ T cell responses to model antigens and to cancer neoantigens." (PMID 34396986, 2021). "Significant associations have been verified by multiple studies between the clinical outcome of cancer patients and CD4+ T cells, CD8+ T cells, B cells, dendritic cells, natural killer cells, and mast cells." (PMID 34745939, 2021). "In the present study, CD4+CD45RO+ T cells from the lesional blood highly expressed genes relating to cancer progression and CTCL progression." (PMID 34608214, 2021). "In our study, we found that the prolonged CD4+ T cell polyclonal stimulation leads to the induction of the exhaustion process, which is dramatically accelerated by cancer cells." (PMID 34439305, 2021).